TLR3 (toll like receptor 3)
Diseases named in the same sentence as TLR3 in open-access papers (continued):
Sharing a sentence is not in itself a finding about the gene and the disease.
infection (continued). "In summary, co-depletion of LEDGF, ADAM10 and Nup153 replicated the effects, in terms of modulation of susceptibility to infection and viral DNA detection, observed through increased levels of miR-155 both in the context of TLR3 stimulation and ectopic expression in primary human MDMs." (PMID 23028330, 2012). "Alternatively, it may be that the primary advantage gained by HAV in antagonizing TLR3 signaling is impaired production of proinflammatory cytokines and reduced inflammation associated with the infection." (PMID 21931545, 2011). "To examine the role of TLR3 in the development of TMEV-induced disease, we compared the development of clinical signs and viral loads in the CNS of control B6 and TLR3-deficient B6 (TLR3KO-B6) mice following infection with the BeAn strain of TMEV (1 × 106 PFU)." (PMID 22189096, 2011). "Furthermore, TLR-3 −/− mice are less susceptible to infection with pathogenic RABV, as seen by increased survival and lower viral titers in the brains of TLR-3 −/− animals compared to wt mice." (PMID 20661430, 2010). "Similarly, greater numbers of subepithelial TLR3+ cells during infection were associated with worse rhinovirus-induced AHR (lower day 6 histamine PC10 values; r = −0.51, P = .014) and reductions in FEV1 (r = −0.44, P = .034), as were numbers of RIG-I+ cells (r = −0.68, P = .001)." (PMID 29698627, 2019). "The up-regulation of TLR2 and TLR3 may confer an enhanced ability for pathogen recognition, whereas their reduced expression may lead to an inadequate response and therefore an increased risk of infection." (PMID 30374345, 2018). "TLR3 preferentially senses double-stranded RNA (dsRNA) species, which can originate from some viruses, and TLR3 is associated with induction of innate immunity in response to infection with West Nile virus, respiratory syncytial virus, and encephalomyocarditis virus." (PMID 23316484, 2012). "Activation of TLR3 by poly(I:C) or by endogenous mRNA ligands, such as those released from necrotic cells, induces secretion of pro-inflammatory cytokines and chemokines, a finding that suggests that TLR3 agonists modulate disease outcome during infection-associated inflammation." (PMID 19486528, 2009). "In order to determine whether increased mortality in TLR3 deficient mice resulted from an inability to control viral replication, viral titers in the pancreas, liver and heart were determined by plaque assay at day 3 and 7 post-infection (PI) with CB4." (PMID 19122812, 2009). "trachomatis infection, increased the expression of Toll-like receptor 3 (TLR3), and silencing or knocking-out TLR3 prevented the synergistic effect between infection and IFN-I." (PMID 42294684, 2026). "Microglia quickly detect viral pathogen-associated molecular patterns (PAMPs) through PRRs, such as TLR3 and TLR7, responding within minutes of infection." (PMID 41503211, 2026). "An in vitro infection of murine BMDMs isolated from TLR2-, TLR3- TLR4-, TLR7-, TLR9-, TLR2/TLR4-, and TLR2/TLR4/TLR9- deficient mice and cultured with Mtb showed that TLR9 was critical for protection against infection via FLT-3 ligand-generated DCs." (PMID 41236793, 2025). "The induction of viral RNA sensors (TLR3 and RIG-I), along with associated factors (IRF3, IFN-β, and OAS2), was low on the first day post-infection and reached peak expression by the third day." (PMID 41303574, 2025). "Severity of infection measured by the 8-category ordinal scale (OS), where 1 is not hospitalized and 8 is death, positively correlated with platelet-TLR3 and leukocyte-TLR5, while leukocyte-TLR7 showed an inverse correlation." (PMID 40825056, 2025). "Infection with ARV significantly upregulated the mRNA expression levels of TLR3 and TLR5 in host cells." (PMID 40059215, 2025). "Administration of TLR4 or TLR3 agonists or intranasal infection of mouse-adapted influenza virus (H1N1) or coronavirus (MHV-A59) induced CD69 in lung ECs." (PMID 40617350, 2025).
infection (continued). "Previous studies demonstrate that tlr3 is involved in the activation and recruitment of antiviral genes to the site of infection." (PMID 40906234, 2025). "The genes ITGA4 and TLR3 were related to initial rejection and innate immune response infection of H. contortus in Florida Native sheep." (PMID 39883377, 2025). "While this loop amplifies antiviral and antifungal signals, excessive or sustained TLR3 activation under specific conditions—such as in immunosuppressed hosts or in high-dose infections—can trigger excessive production of proinflammatory cytokines." (PMID 41459537, 2025). "In response to infection, the EV-A71 2A protease has been shown to reduce the TLR3 protein level in neuroblastoma cells, and is responsible for its subsequent cleavage." (PMID 41472211, 2025). "Multiple pattern recognition receptors, such as the toll-like receptor 3 (TLR-3), have also been demonstrated to be involved in controlling viral replication in the murine models of infection." (PMID 40732672, 2025). "After infection, the TLR3 protein expression was significantly elevated compared with uninfected liver (**P < 0.01)." (PMID 38172683, 2024). "For example, a totivirus within the protozoan parasite Leishmania guyanensis is recognised by TLR3 following infection with the parasite, launching a hyper-inflammatory response, and amplifying the host’s susceptibility to the infection." (PMID 39194910, 2024). "Previous studies have shown that the TLR3-NF-κB pathway is activated following infection with dsRNA viruses leading to proinflammatory cytokine release." (PMID 38860860, 2024). "It is known that infection with the SARS-CoV-2 virus is accompanied by an increase in the expression of TLR3 and TLR7." (PMID 39457048, 2024). "While evaluating different treatment regimens using the TLR3 agonist Poly (I:C), we observed higher than expected variability in lethality following infection of the transgenic hamsters." (PMID 39459957, 2024). "The expression kinetics demonstrated the existence of S. japonicum infection-induced TLR3 expression in C57BL/6 mouse livers at early time points following infection." (PMID 38172683, 2024). "We identified important genes DE in both our in vitro and in vivo infection models consistent with previous studies, namely, TLR3, IFIH1 (MDA5), SOCS1, OASL, DDX60, STAT1, MX1, CMPK2, LY96 (MD-2), STAT1, STAT2, TRIM25, IRF7, and IFIT5." (PMID 38675946, 2024). "The difference in the prevalence of TLR3 rs3775291, another TLR3 variant, between chronic HBV patients and healthy Caucasian individuals with resolved infection was concluded to contribute to the lower risk of HBV persistence." (PMID 38907187, 2024). "The intricate interaction between the Avian Influenza Virus (AIV) and the host immune system, primarily through the Toll-like receptor 3 (TLR3) pathway, is central to inflammatory response development and immune regulation following infection." (PMID 38731436, 2024). "In PK-15 cells, SVA downregulates the expression of host lncRNA320, which is involved in the regulation of the TLR3 signaling pathway via the lncRNA320-sc-miR-7-CCR3 axis to promote IFN-β expression in response to SVA infection." (PMID 38581048, 2024). "The initial infection with virus will activate antiviral TLRs like TLR3, 7, 8, 9 in the first few minutes/hours after infection." (PMID 38550582, 2024). "After infection, TLR3 expression and p-NF-κB levels increased in cholangiocytes, leading to increased release of CXCL9 and CXCL10." (PMID 38860860, 2024). "For this purpose, we used models of Toll-like receptor 3 (TLR3)-mediated lung inflammation or RSV infection followed by the secondary infection with S. pneumoniae at different time points in young mice." (PMID 39766307, 2024). "The employment of different si-RNAs for TLR3 silencing resulted in variations in NF-κB mRNA responses at 36 and 48 h post-infection (p < 0.0005), suggesting specificity in the si-RNA-mediated modulation of NF-κB." (PMID 38731436, 2024).
infection (continued). "Interleukin (IL)-1 and Interleukin (IL)-6 was one of the cytokines induced by TLR3 that was essential to efficient response to tissue repair against trauma or infection." (PMID 38322849, 2024). "Upon infection, influenza viruses trigger innate immune responses mediated by PRRs, such as TLR3, TLR7, TLR8, cytosolic receptor RIG-I, and NOD-like receptor NLRP3." (PMID 38892370, 2024). "A systematic search for relevant studies was performed using PubMed, Scopus, SciELO, Google Scholar, and Science Direct by the MeSH descriptors and the Boolean Operator “AND”: “Infections”; “TLR3”; “SNP”, between January 2005 and July 2022." (PMID 37510216, 2023). "The toll-like receptor signaling pathway was highly enriched at 48 hpi, showing that Tlr2 and Tlr3 were upregulated during infection." (PMID 37963152, 2023). "Regarding CHIIKV infection, TLR3 agonist treatment inhibits CHIKV replication in vitro by upregulating IFN- β and other pro-inflammatory cytokines; this response also resulted in positive feedback on TLR3 expression." (PMID 37766276, 2023). "Inhibition of TLR3, 4, 7 were observed in PAMs or/both immature DCs at 6 h post-infection (hpi), and abolished at 24 hpi." (PMID 37007469, 2023). "Genes involved in the TLR3 and interferon-stimulated gene 56 families, both of which are heavily increased at post-infection, will mediate cytokine production by regulating transcription of type I/II IFNs." (PMID 37211158, 2023). "In fact, TLR2 blockade and TLR3/7 knockdown stimulated T. cruzi growth, suggesting that these molecules play a significant role in the host cell response to infection." (PMID 37799608, 2023). "Coronaviruses, including SARS-CoV-2, produce dsRNA early during the infection cycle, which is recognized by the viral dsRNA receptor, TLR3." (PMID 37704739, 2023). "In considering these opposing findings, it has been suggested that the role of TLR3 in the flavivirus immune response changes throughout the different stages of infection." (PMID 36851477, 2023). "TLR6 (respectively) and TLR7 (respectively) were significantly overexpressed in infection-derived EVs compared to control-derived EVs, while TLR3 (respectively) was expressed but significantly unchanged within EVs." (PMID 36979955, 2023). "In a study employing RV infection of human bronchial epithelial cells, TLR3 was constitutively expressed while MDA5 and RIG-I were induced later during infection in response to TLR3 and IFN signaling." (PMID 36810092, 2023). "This analysis also confirms our previous findings of an enrichment in rare pLOF variants of 13 genes involved in TLR3- and IRF7-dependent type I IFN immunity to seasonal influenza virus in critical cases relative to controls with mild/asymptomatic infection." (PMID 37020259, 2023). "Reduced expression of interferon-responsive genes, IL-6, IL-1, IL-1, CCL5, and TNF-, was evidence that TLR3 signaling was downregulated during a live MPOX infection." (PMID 37533932, 2023). "In summary, our present results suggest that TLR3 is a pattern recognition receptor (PRR) gene in the immune response to pathogen infections in hybrid yellow catfish." (PMID 36670828, 2023). "Infection of porcine alveolar macrophages (PAMs) with PRRSV significantly reduced the ability of these cells to respond to TLR3 ligation." (PMID 37007469, 2023). "Next to triggering the TLR3 response, direct infection of HBMECs with Dengue virus was also shown to induce ROS, resulting in HBMEC death and higher endothelial permeability." (PMID 36851477, 2023). "Since the odontoblastic differentiation of SCAP has long been elusive, particularly in the presence of infection, this is the first line of evidence that suggests that TLR3 is involved in odontoblastic differentiation." (PMID 37887345, 2023). "EV71 is a highly infectious RNA virus that induces type III interferon (IFN-γ) production after infection by stimulating the toll-like receptor 3/interferon regulatory factor 1 (TLR3/IRF1) signaling pathway." (PMID 37649892, 2023).
infection (continued). "In the bat intestinal organoids, rapid and robust induction of the TLR3 response induced the bat cells to prevent virus propagation in the early phase of infection." (PMID 37191444, 2023). "Viral infections from the basolateral side of the IECs elicit a stronger intrinsic immune response in comparison to the luminal apical infections; moreover, clathrin-sorting AP-1B mediated polarized sorting of the TLR3 towards the basolateral side of the IECs." (PMID 37191444, 2023). "TLR7 binds to ssRNA in the endosomal membrane, while TLR3 is activated by dsRNA species generated during IvA infection." (PMID 37773712, 2023). "Endosomal TLRs, and in particular TLR3, participate in the detection of flaviviruses in certain cell types, as well as in the physiopathology of infection, but their involvement in the induction of the IFN response is relatively modest." (PMID 37965539, 2023). "Toll-like receptor 3 (TLR3) is a pattern recognition receptor mainly known for its role in innate immune response to infection." (PMID 37414800, 2023). "There have also been reports of Cryptosporidium derived RNAs to be trafficked into the host cell nucleus during infection providing an additional potential trigger for TLR3." (PMID 35584177, 2022). "Consistently, we uncovered a key determinant in the envelope (E) protein that both augments the probability for one physical virus to initiate infection in certain cell environments and mediates resistance to the TLR3-induced antiviral response." (PMID 36271143, 2022). "It was reported that TLR3 mRNA levels in the liver, kidney and spleen of channel catfish were significantly up-regulated at different time points after infection with Edwardsiella ictaluri." (PMID 36292749, 2022). "During RABV infection, TLR3 maintains some endosomal localization; however, two days post-infection, TLR3 relocalizes to the center of these perinuclear Negri bodies." (PMID 35409387, 2022). "Previous studies on TLR3 were mainly focused on inflammation and infection, but there were few studies on the expression of TLR3 in tumors, the effect of TLR3 on tumor prognosis and the related biological functions of TLR3." (PMID 36419829, 2022). "Although single-PEDV infection showed up-regulation on cell-membrane- (TLR4) and endosomal-associated (TLR3 and TLR8) TLRs by 5 DPI, it seems that these TLRs did exert a sufficient modulatory effect on MyD88 and TRIF." (PMID 36376395, 2022). "In an additional in vivo mouse model of chronic wound infection, mice treated with TLR3 activated MSC demonstrated migration to the site of infection, which was mechanistically shown to be mediated in part by upregulation of CXCR4 expression." (PMID 36356087, 2022). "Together, Tsai and Liang began to map out the essential role of TLR3 regarding infection control and cytokine and IFN production." (PMID 35632732, 2022). "Upon IBV M41 strain infection, the TLR3-TRIF signaling pathway was highly activated, which further triggered the innate immune response and inhibited IBV replication." (PMID 35955436, 2022). "The results imply that the oral infection of IBDV results in a rapid activation of the TLR3 antiviral signaling pathway in ILP cells during the first hours of infection." (PMID 35215986, 2022). "In the present study, TLR3 expression was upregulated on the first day after infection, suggesting that TLR3 in fish also plays a role in resistance to bacterial infection." (PMID 36439120, 2022). "The resistance to TLR3-induced antiviral response can result from a faster onset of infection by the passaged viral populations." (PMID 36271143, 2022). "Thirdly, kinetic analysis demonstrated that the adapted viral populations showed enhanced resistance to TLR3-mediated inhibition at later time-points post-infection, and with higher viral input." (PMID 36271143, 2022).
infection (continued). "An earlier study reported significantly elevated expression of TLR3 in individuals who spontaneously cleared the virus, suggesting a protective role of TLR3 in HCV genotype 3 infection." (PMID 35628287, 2022). "We next utilized ChIP-qPCR to investigate how the acetylated histone H3 chromatin occupancy in the TLR3 promoter region be regulated by YAP/TAZ upon infection." (PMID 35503798, 2022). "By applying a PRR agonist such as the MDA5/TLR3 agonist Poly(I:C), the innate immune inhibitory effect of the virus can be overruled if applied locally at an early stage during infection." (PMID 35215785, 2022). "Next, we measured IFNλ secretion from ileal punches of infected Tlr3-/- mice and wild type controls at day 2 of infection by ELISA." (PMID 35584177, 2022). "We also compared expression of NRF2-target genes, Hmox1 and Nqo1, in WT and Tlr3-/- cells at 8 hrs post-infection." (PMID 33765083, 2021). "More proximal loss-of-function defects, such as those found in TLR3 or in the adaptors MyD88 and IRAK-4, are associated with a restricted cadre of infections." (PMID 34199501, 2021). "There is precedent from murine norovirus (MNoV) that TLR3 contributes to controlling infection in vivo." (PMID 34205050, 2021). "Following infection of chickens with E. tenella, TLR3 and 15 were also up-regulated in the intestine and spleen beside TLR1A, 4, 5, 7 and 21 in caecum." (PMID 34579197, 2021). "The infection with rNDV-H5 induced a dramatic increase in TLR3 expression in comparison to NDV LaSota, suggesting that the expression of exogenous H5 by the vector modified the way it is recognized by the innate immunity sensors." (PMID 34358174, 2021). "Consistently, in vitro studies with monocyte-derived DCs (moDCs) showed that infection with hMPV leads to an increased expression of TLR3." (PMID 33809875, 2021). "Changes in TLR3 signaling induction of IFN-β compared to MDA5 signaling after infection with the same virus are further reflected in the ratio of sera IFN-β versus IFN-α levels." (PMID 34804036, 2021). "Disease incidence in TLR3+/- mice continued to rise to 50% by day 20 post-infection, just under the 60% disease incidence observed in TLR3+/+ mice." (PMID 34804036, 2021). "TLR3 expression, at reduced levels in TLR3+/- mice, is not successful in protecting from CB4-induced T1D as up to 16 days post-infection, TLR3+/- mice show a higher incidence of T1D compared to infected control wild type TLR3+/+ mice." (PMID 34804036, 2021). "In vitro studies using A549 cells have demonstrated that the expression of TLR3 is upregulated upon infection with hMPV, with a peak at 9 hours post-infection (p.i.)." (PMID 33809875, 2021). "Infection with S. Typhimurium increased bacterial and cell growth in a time-dependent manner; however, treatment with poly(I:C)—a TLR3 agonist—decreased cell growth and intracellular bacterial growth by approximately 3–5-fold." (PMID 34564417, 2021). "Unexpectedly, deletion of TLR3 in mice decreased viral replication and reduced manifestations of infection, suggesting a detrimental effect of the interaction between TLR3 and VACV42." (PMID 34711839, 2021). "More recently, the role of TLR3 in detection of enterovirus A71 (EV-A71) has been studied, suggesting that expression of TLR3 in HEK293 cells enabled them to sense EV-A71 infection, leading to type I IFN mediated antiviral immunity." (PMID 33498715, 2021). "The same report also suggests that silencing of TLR3 in mouse and human primary immune cells impaired the activation of IFNβ upon EV-A71 infection, indicating the importance of TLR3 in EV-A71 infection." (PMID 33498715, 2021). "It has been proposed that TLR3 enhances the infection’s antiviral mechanism and helps track dead infectious cells." (PMID 33534822, 2021). "Among the L. pneumophila-induced cytokines impacted by TLR3 and/or TLR4, IL-6 and IL-1β are associated with increased neutrophil infiltration to sites of infection." (PMID 34280250, 2021).